MMP2 (matrix metallopeptidase 2)
Diseases named in the same sentence as MMP2 in open-access papers (continued):
Sharing a sentence is not in itself a finding about the gene and the disease.
tumor (continued). "Immunofluorescent and an immunohistochemical staining demonstrated that fibrin and MMP-2 were highly expressed in tumor tissue (–7)." (PMID 29686590, 2018). "Some studies report the high expression of MMP-2 in several types of cancer, among them the GC, and for that reason the inhibition of this metalloproteinase becomes a potential attempt to control tumor progression and metastasis." (PMID 29385675, 2018). "The MMP-2 and -9 are involved in tumor angiogenesis mostly via their matrix-degrading capacity and neovascularization potential." (PMID 30518369, 2018). "Dual targeting of fibrin-fibronectin complexes and MMP-2/9 in tumor tissues lays the foundation for achieving tumor-targeting and tumor-specific cell penetration." (PMID 29686590, 2018). "A high production of MMP-2 and MMP-9 increases the migration and invasion of tumor cells and is associated with a poor prognosis in cancer patients." (PMID 30235848, 2018). "Matrix metalloproteinase-2 (MMP-2) expression in the tumour-invaded areas was only seen in the proximity of inflammatory cells and blood vessels." (PMID 29623449, 2018). "Prior studies have shown that increased expression of key tumor microenvironment components such as collagen and MMP2/MMP9 are necessary for tumor epithelial extravasation." (PMID 30458886, 2018). "In this regard, tumor-derived EVs harbor matrix-degradation proteases including matrix metalloproteinase-2 (MMP-2) and MMP-9, which correlated with tumor progression." (PMID 29696020, 2018). "MMP-2 has been demonstrated to play an important role in mediating tumor invasion in many types of cancer cells." (PMID 30359388, 2018). "As MMP2 is normally produced by resident tumour cells, the reduced amount of MMP2 found in AQP1 siRNA‐treated tumours is first of all the consequence of the reduced number of tumour cells." (PMID 29044946, 2018). "The shrinkable nanoparticles then penetrated deep into the tumor through the leaky tumor blood vessel, actuated by the degrading gelatin particles via MMP-2, which allowed small-size gold nanoparticles and the anticancer drug doxorubicin to be released." (PMID 30340364, 2018). "It has been demonstrated that hsa-miR-29b is capable of repressing tumor angiogenesis, invasion and metastasis, by targeting metalloproteinase-2 (MMP2)." (PMID 29361687, 2018). "The pro-drug was cleaved by MMP-2 substrate polymer when used in conjugation with methotrexate that inhibited tumor growth." (PMID 30647857, 2018). "MMP2 and MMP9 expression is associated with tumour cell invasion, and is elevated in various malignancies including HCC." (PMID 29346427, 2018). "Two different prodrugs of PTX (i.e., PTX-2'AcG and PTX-7AcG wherein the 2'- and 7-hydroxyl groups were conjugated to C-terminus of glutamine of octapeptide) were found to be vulnerable to cleavage by the MMP2 at tumor site, to release PTX." (PMID 30429787, 2018). "More than 20 MMPs have been described and MMP-2 and MMP-9 are strongly associated with tumor spread and invasiveness." (PMID 30235848, 2018). "The present study showed that the addition of MMP-2 to the medium during incubation of tumor cells with FITC-iCREKA allowed FITC-iCREKA to penetrate into tumor cells." (PMID 29686590, 2018). "Numerous studies have shown that MMP-2/9 are highly expressed in tumor tissues, which promotes the formation, repair, and maturation of tumor neovasculature and stimulates tumor growth." (PMID 29686590, 2018). "NF-κB binding sites were identified in the promoters of genes that encode several matrix metalloproteinases (MMPs) including MMP-2, MMP-9, and so forth, which degrade the extracellular matrix (ECM) to facilitate tumor cell invasion in tissues." (PMID 29361914, 2018). "The nanoprobe was reported to be turned on by the presence of MMP-2, leading to enhanced cellular uptake and the restoration of fluorescence, thereby enabling the visualization of nanoparticles within tumor tissue." (PMID 30155269, 2018).
tumor (continued). "TGF-β promotes tumor invasiveness through MMP-2, MMP-9, MT-MMP1 and urokinase-like plasminogen activator is up-regulated in both pancreatic ductal adenocarcinoma and hepatocarcinoma." (PMID 30216977, 2018). "HG-CD147 is highly expressed on the cell surface of a variety of tumor cells and can promote metastasis through inducing MMPs, especially MMP-2 and MMP-9, in tumor cells." (PMID 29719608, 2018). "Herein, we used ALT-C as a α2β1 integrin ligand to study the effect of ALT-C on MMP-9 and MMP-2 expression as well as on tumor cells, fibroblats and endothelial cell migration." (PMID 29713337, 2018). "In conclusion, the data strongly indicated that the selected compound 16 inhibit tumor invasion and migration by repressing MMP-2 and MMP-9 at protein and mRNA levels." (PMID 29679218, 2018). "Dtxl-8P4 NPs greatly suppressed the expression of CD31 and MMP2, compared with other groups, verifying that tumor proliferation and metastasis were effectively restricted." (PMID 29541026, 2018). "Particularly, upregulations of MMP2 and MMP9 are associated with NPC tumor progression and enhance the migration and invasion of NPC cells." (PMID 29416735, 2018). "Neurotrophic factors and pro-matrix metalloproteinase-2 (MMP2) secreted from astrocytes promote tumor growth." (PMID 30186118, 2018). "In particular, MMP2 activity plays an important role in endothelial cell migration, a key feature of tumour angiogenesis." (PMID 29044946, 2018). "It has been documented that Matrix metalloproteinases (MMPs) play a crucial role in tumor invasion and metastasis by degradation of the extracellular matrix, and high level expression of MMP-2 and -9 is correlated with an aggressive cancers." (PMID 30960968, 2018). "The linker component PLGLAG is predominantly sensitive to an enzyme called matrix metalloproteinase 2 (MMP-2), and this enzyme-sensitive substrate strategy was employed for tumor targeting of DOX." (PMID 29405790, 2018). "In the present study, IHC method was used to evaluate angiogenesis and metastasis in tumor tissues by MMP2, MMP9, VEGF, and CD31 markers assay." (PMID 30127820, 2018). "Remodeling tumor stroma and pro-angiogenesis: IL-33 markedly stimulates myofibroblasts to produce several types of extracellular matrix components including MMP2, MMP9, and growth factors associated with CRC tumor growth, progression and metastasis." (PMID 30547011, 2018). "High MMP-2 expression in primary lesion contributes to invasiveness of primary tumour cells, leading to metastases and poor survival outcomes." (PMID 29492694, 2018). "Activating MMP2 generates type IV collagenase, which can degrade the proteins of the extracellular matrix of tumor cells, leading to tumor cell invasion and metastasis." (PMID 29850505, 2018). "We have developed a unique DDS for bienzyme-responsive tumour targeting and drug-controlled release based on MMP-2-catalysed degradation of gelatin and Hyal-catalysed degradation of HA." (PMID 29410811, 2018). "COMP induced CD36-dependent activation of MEK/ERK and PI3K/AKT, and a panel of tumor-promoting factors, including EMT makers, MMP-2/9, Slug and Twist, so as to promote its tumor-promoting effects." (PMID 30231922, 2018). "In general, it is considered a suppressor of tumor angiogenesis and a potential tumor suppressor, in part through its inhibition of the gelatinases, MMP2 and MMP9." (PMID 29581841, 2018). "Recent studies have shown a correlation between increased MMP2/MMP9 gene expression in tumour tissues and clinical status, histopathological grading, and metastasis occurrence." (PMID 30595764, 2018). "Studies have also shown that the combination of CXCL12 and its receptor CXCR4 can activate NF-κB and increase the secretion of MMP-2 in tumor cells." (PMID 29305742, 2018). "Previous studies have reported the increased levels of MMP2 in NSCLC population and that the level of MMP2 served as an indicator of the extent of tumor metastasis." (PMID 29558998, 2018).
tumor (continued). "Further investigation is needed to elucidate the role of MMP-2 and -9 in the pathogenesis of endometrial hyperplasia and neoplasia." (PMID 30022838, 2018). "Among the MMPs, MMP-9 and MMP-2 are abundantly expressed in various malignant tumors and are considered to play critical roles in tumor metastasis." (PMID 30574046, 2018). "ERK1/2 activation stimulates its downstream signaling molecules including PI3K/MMP-2, which can promote the formation of VM by inducing tumor extracellular matrix (ECM) remodeling." (PMID 30052652, 2018). "In conclusion, FUT175 enhances the anti-tumor effect of radiotherapy through downregulation of NF-κB and reduces IR-induced tumor invasiveness by directly inhibiting MMP-2/-9 in CRC cells." (PMID 30336548, 2018). "As for MMP-2 in glioblastoma, the activity is increased along with the tumor grade and the expression is significantly higher than that in normal brain tissue." (PMID 29495404, 2018). "MMP-2 is involved in tumor-induced and radiation-enhanced migration and invasion, and pre-treatment with andrographolide significantly decreased MMP-2 expression in irradiated cells, which reduced migration and invasion." (PMID 30359388, 2018). "Prevention of tumor growth was related with suppression of COX-2/MMP2, ZEB1 and zinc finger protein SNAI1 (SNAI1)." (PMID 30445746, 2018). "Although inhibition of MMP-2 expression suppresses the invasiveness of tumor cells in several model systems, the molecules inducing MMP-2 activation during tumor development had not been defined." (PMID 29903032, 2018). "Several studies have shown that FAK/PI3K/AKT/mTOR signaling is involved in cell proliferation, differentiation, survival and tumor metastasis, and the signaling pathway is also involved in the regulation of MMP-2 and MMP-9." (PMID 29280977, 2017). "To support that tumor cells express MMP-2, we performed immunofluorescence on a GBM cell culture (T86)." (PMID 28234925, 2017). "Activated MMP-2/9 facilitates the passage of tumor cells through the ECM and the basal membrane of the blood vessel wall, promoting the invasion of tumor cells." (PMID 29147947, 2017). "When miR-29a production is decreased, tumor cells are able to express MMP2 in the large quantities necessary for their invasion and apoptosis escape." (PMID 29206174, 2017). "Due to the common characteristic invasive behaviour of trophoblast cells and tumour cells, the molecular pathways (MMP2/MMP9) of these two types of cells are strikingly similar." (PMID 28032589, 2017). "We further determined the activity of MMP-9 and MMP-2 which are considered to be most crucial markers in tumor invasion due to their ability to degrade the extracellular matrix (ECM)." (PMID 29299144, 2017). "LRP1 not only regulates tumor invasion and migration through metalloproteinase MMP-2 and MMP-9 expression, but it also inhibits cell apoptosis by affecting caspase-313." (PMID 29138479, 2017). "Our results suggest LIUS and DOX combination treatment suppresses tumor growth, prolongs survival, increases the expression of MMP-2 and MMP-9, and promotes the deposition of collagen fibers in OSCC xenograft." (PMID 29157266, 2017). "Matrix metalloproteinase 2 and 9 (MMP2 and -9) are also known to participate in cell invasion during enhanced tumor progression." (PMID 28187439, 2017). "All this suggests a role for WFCD2 in rebuilding the tumor microenvironment by regulating the expression of MMP2 and CD44." (PMID 28679402, 2017). "Of which, one study used the percentage of positive cells after IHC to calculate the ratio, and the results showed that with the increase of tumor grade, MMP-2/TIMP-2 rose from 1.00 to 1.18." (PMID 26729052, 2017). "The expression of MMP-9 and MMP-2 is considered an important sign of tumor invasion due to the critical roles the basement membrane plays in the process of tumor invasion." (PMID 29312615, 2017).
tumor (continued). "An increased expression of MMP proteins, such as MMP-2 in tumor cells is often accompanied with increased invasiveness and metastasis, as well as with decrease in overall survival." (PMID 29100268, 2017). "The aim of this study was to investigate the prognostic influence of MMP-2 by performing automated quantitative immunohistochemistry on tumor samples from 89 patients diagnosed with WHO grade II-IV astrocytic brain tumors." (PMID 28234925, 2017). "Lastly, in NMIBC, univariate analysis demonstrated that age, gender, tumor grade, tumor stage (Ta/Tis vs. T1) and expression of MMP-2, RB and PAI-1 predicted overall survival (OS)." (PMID 29245935, 2017). "U266 cells also express MMP-2 in the tumor-bone microenvironment as determined by immunofluorescence." (PMID 28611279, 2017). "In particular, abnormal expression of MMP2 and MMP9 has been frequently detected in solid tumor tissues and is associated with tumor metastasis in many cancer types." (PMID 28114404, 2017). "Since EMT is also associated with the acquisition of migratory and invasive properties of tumor cells, we also examined the expression of MMP-2 and MMP-9." (PMID 28801561, 2017). "This study also found a higher level of MMP2 expression in the stroma of tumours, with the highest immunoreactivity found in the fibroblasts closest to the epithelial cells." (PMID 28531107, 2017). "MMP2 is a metalloproteinase secreted by CAFs and also tumour associated macrophages and functions by remodelling the ECM, resulting in tumour progression, invasion, and metastasis and the support of angiogenesis." (PMID 28531107, 2017). "In our study, MMP-2 was expressed by tumor cells in all tumor grades and was mainly located in the cytoplasm, but also in the membrane." (PMID 28234925, 2017). "Among the protease, the metalloproteases (MMPs) play a critical role in tumor spread, in particular the MMP2 and 9 are the most commonly involved in the extracellular matrix reassembly and tumor progression." (PMID 29023465, 2017). "Some studies suggest that the PI3K/AKT signaling pathway can promote tumor invasion and metastasis by controlling the expression of MMP-2 and MMP-9." (PMID 29157266, 2017). "For instance, gelatinases MMP-2 and MMP-9 are highly associated with tumor progression and both can effectively cleave Fibulin-2." (PMID 28099917, 2017). "Overexpression of MMPs-3, -11, -12, and -13 was detected in tumor stroma, along with MMP-2 in transformed mammary epithelial cells." (PMID 29112161, 2017). "Forward selected, proportional Cox regression of survival modifying parameters (T, N, R, G, tumor localization, MMP2/9, TIMP1/2, CXCR4, and CXCL12) identified CXCR4 being the only survival-modifying parameter in HNSCC." (PMID 29348861, 2017). "Collectively, these findings suggested that CCR4 promote cancer metastasis and tumor angiogenesis through the up-regulation of MMP2 via ERK/AKT pathways in HCC." (PMID 28959024, 2017). "Notch signalling pathway is critical in cell proliferation and apoptosis and the MMPs are important in facilitating tumour invasion so that active MMP-2 is considered a cancer metastasis indicator." (PMID 28903355, 2017). "The cannabinoid anti-tumor activity also acted through Notch-1 signalling pathway inactivation and MMP-2 down regulation." (PMID 28903355, 2017). "MiR-373 act as a tumor suppressor role during BCa progression by recovering E-cadherin expression which leads to down-regulation of Cyclin D1, C-myc and MMP2, therefore inhibits cells proliferation, migratory and invasive capacity." (PMID 29212202, 2017). "The MMP-2 intensity in cytoplasm/membrane was quantified by a trained software-based classifier using systematic random sampling in 10% of the tumor area." (PMID 28234925, 2017). "In breast cancer cell line MDA-MB-231, AST-IV inhibited the viability and invasion of tumor cells, downregulated the expression of Vav3, MMP-2, and MMP-9 through suppressing the activation of ERK1/2 and JNK." (PMID 29344421, 2017).
tumor (continued). "MMP-2 destructs mesenchymal collagen or the ECM together with adhesion molecules in the process of tumor invasion and metastasis." (PMID 28467517, 2017). "MMP-2 and MMP-9 are thought to be important in tumor metastasis and tissue remodeling; therefore, the present study investigated the protein expression of MMP-2 and MMP-9 during the treatment of MCF-7 or MDA-MB-231 cells with propoxur." (PMID 29152067, 2017). "In conclusion, we revealed evidently that estrogen promotes NSCLC tumor metastasis through ERβ by increasing MMP-2, and p38MAPK and AKT activities also should be considered as molecular parameters in this progression." (PMID 28915603, 2017). "Here, we found that ADSCs promoted tumour growth and invasion by increasing matrix metalloproteinase 2/9 (MMP2/9) expression in tumour cells." (PMID 28423603, 2017). "MMP2 is involved in tumor pathogenesis, which plays a key role in tumor cell invasion and metastasis." (PMID 29069837, 2017). "Similar with that of HCT116, MIIP S303A expression which blocked promoter-enrichment of MIIP or RelA Ac-K310 in CaCo2 cells, inhibited transcription of MMP2 and Twist and tumor cell invasion." (PMID 29038521, 2017). "It has been shown to enhance tumor cell migration by increasing MMP-2 expression, to inhibit antitumor immunity by blocking the response of immune cells to IL-12, and to act antiapoptotically by inducing or inhibiting different signaling pathways." (PMID 28545495, 2017). "For example, IL-4 is known to induce cathepsin protease activity and upregulation of Toll-like receptor 2 signaling and attenuation of glucose transporter 1/membrane type 1-MMP/MMP2 pathway are involved in tumor expansion and invasion." (PMID 27965469, 2017). "Recently, both 18F-NOTA and 68Ga-NOTA labeled to C6 (another selective gelatinase inhibitor) have been studied as potential radiopharmaceuticals for the imaging of in vitro MMP2 activity in tumor models." (PMID 28846661, 2017). "IL-8 can also influence matrix remodeling through the regulation of matrix metalloproteinase-2(MMP-2), resulting in enhanced tumor invasiveness." (PMID 28383487, 2017). "The formation of new blood vessels contributes to tumor growth and is under the regulation of important proangiogenic factors such as MMP-2 and MMP-9." (PMID 29238715, 2017). "We also evaluated the effect of Rhy on the expression of CXCR4, MMP-9, and MMP-2, proteins which play a critical role in tumor metastasis." (PMID 28534824, 2017). "VEGF as well as type IV collagenases MMP2 and MMP9 produced by M2-like TAMs not only promote tumor growth and angiogenesis, but also cause vascular permeability to facilitate tumor migration." (PMID 28467800, 2017). "This impaired tumor growth, the migration and invasion of the cells, and MMP-2, MMP-9, integrin β1 and Bcl-2 were involved in these processes." (PMID 28350359, 2017). "MMP2 can degrade the extracellular matrix, which increases the spaces between cells and provides a favorable environment for the formation of tumor blood vessels, and it can also enhance endothelial cell migration." (PMID 28592924, 2017). "Increased NRP1 expression upon upregulation of VEGFA, secretion of MMP-2 and -9, and activation of αvβ5 integrin furthermore correlates with tumor cell invasiveness and VM." (PMID 29112161, 2017). "TIMP2 is an important endogenous inhibitor of MMPs which combines with MMP2 preferentially and can regulate the tumor growth, invasion and angiogenesis by a variety of mechanisms for MMP-dependent or MMP-independent pathways." (PMID 27835587, 2016). "RASSF10 acting as a tumor suppressor to inhibit HCC invasion partially mediated by Focal Adhesion Kinase or p38 MAPK to decrease the accumulation of MMP2." (PMID 27348267, 2016). "STAT1 negatively regulates angiogenesis, tumorigenicity, and metastasis of tumor cells by inhibiting the expression of bFGF, MMP-2, and MMP-9." (PMID 26928402, 2016).